RHOC (ras homolog family member C)
Diseases named in the same sentence as RHOC in open-access papers (continued):
Sharing a sentence is not in itself a finding about the gene and the disease.
lung adenoma (1 paper, 2015). A benign, well circumscribed epithelial neoplasm that arises from the bronchus or the lung parenchyma. "Our study of the relationship between RhoA, RhoC and K-Ras in murine lung adenoma formation sheds light on the broader subject of cellular signal transduction networks, and how signal redundancy and compensation in these networks can result in counterintuitive results when the network is modified." (PMID 26030593, 2015). "Moreover, we found that deletion of either RhoA or RhoC alone did not suppress K-RasG12D induced lung adenoma initiation." (PMID 26030593, 2015).
malignant meningioma (1 paper, 2016). "In our hands, targeting of DLC1-v1 with specific shRNA in KT21cells established from human malignant meningioma resulted in enhanced activity of RhoA/RhoB/RhoC GTPases as shown in active RHO pull down assay and increased cell migration in scratch assay." (PMID 27614886, 2016).
myeloma (1 paper, 2019). "This study aimed to explore the effects of RhoC downregulation on the cytoskeleton, pseudopod formation, migration ability, and canalization capacity of myeloma vascular endothelial cells (MVECs) in vitro." (PMID 31062507, 2019).
pancreatic disease (1 paper, 2023). "Among these proteins, six (AAT, IGFBP2, RAB2B, PRDX2, RHOC, and LMNA) with functions closely related to pancreatic disease were selected for further validation." (PMID 36712921, 2023).
prostate tumour (1 paper, 2015). "Interestingly, a recent study has revealed that RhoC predominately associates with PRK3 in prostate cells leading to metastatic prostate tumour growth downstream of a hyperactive PI3′K pathway." (PMID 26296974, 2015).
sarcopenia (1 paper, 2024). Progressive decline in muscle mass due to aging which results in decreased functional capacity of muscles. "Our results suggested that BDNF, JAK2, RhoC, Myh6, Stat5a, Tnnc1, and other genes may mediate the beneficial effects of exercise on sarcopenia through these pathways." (PMID 39309455, 2024). "Transcriptomic analysis identified BDNF, JAK2, RhoC, Myh6, Stat5a, and Tnnc1 as core target genes that may mediate the effects of different exercise intervention stimuli through the JAK-STAT, cGMP-PKG, and Rap1 pathways to improve the skeletal muscle phenotype of sarcopenia." (PMID 39309455, 2024).
tongue cancer (1 paper, 2022). A malignant neoplasm affecting the tongue. "In addition, compared with the 4NQO+captisol group, MK2206 2HCl also significantly reduced MMP-9 and RhoC expression in 4NQO-induced mouse tongue cancers in the 4NQO+MK2206 2HCL group via IHC staining." (PMID 36247874, 2022). "In addition to the occurrence of autophagy, we also found that the tumorigenesis-related factor (MMP-9 and RhoC genes) expression was decreased in vitro and in 4NQO-induced mouse tongue cancers in this study." (PMID 36247874, 2022). "To further detect the mechanism of the chemopreventive effect of MK2206 2HCl, we also detected MMP-9 and RhoC (key regulators of tumorigenesis) expression in OSCC cells and 4NQO-induced mouse tongue cancers through RT-PCR, western blotting, and IHC." (PMID 36247874, 2022).
worm infection (1 paper, 2024). "However, there has been no study on the biological function of RhoC in the response of hosts to worm infection." (PMID 38725025, 2024).
tumor (140 papers, 1998 to 2025). "Its upregulation in gastric cancer tissues and cell lines leads to the suppression of HOXD10, a tumor suppressor gene, resulting in increased expression of RHOC, a gene linked to enhanced metastatic potential." (PMID 39796267, 2025). "Although accumulating evidence has suggested that RhoC is associated with cell invasion and migration and it plays an important role in advanced tumors, evidence regarding the role of RhoC in regulating tumor cell proliferation has been controversial." (PMID 33519932, 2021). "The analysis of TCGA datasets showed that RhoC was overexpressed in tumor tissues and was associated with metastasis in OSCC patients, and these results were consistent with those of a clinical IHC study." (PMID 33519932, 2021). "To further investigate the underlying mechanism, we evaluated the expression of RhoC, Src, and F-actin (the key regulators of tumor cell metastasis) in the MMP-9/shRNA-transfected OSCC cells by real-time PCR, western blotting, and IHC." (PMID 33828938, 2021). "Specifically, RhoC expression has been associated with tumor-node-metastasis frequently observed in OSCC." (PMID 33519932, 2021). "The RHOC gene encodes for the RhoC signaling G protein that, when overexpressed, is involved in cell proliferation and tumor malignancy." (PMID 33112566, 2020). "RhoC has a role in formation of invadopodia and membrane blebs; in fact, RhoC has been implicated in the development of metastatic potential through both extravasation of tumor cells and angiogenesis." (PMID 31200451, 2019). "In order to validate the clinical relevance of our study wherein ROCK2 in association with RhoC regulates radiation response of tumor cells via modulation of DNA repair proteins we performed studies on clinical samples." (PMID 31488179, 2019). "RHOC overexpression is associated with tumor cell proliferation and metastasis and is especially involved in the CRC metastasis signaling pathway, underscoring the prognostic value of PI-containing RHOC expression." (PMID 31578316, 2019). "Third, the closely related RhoA homolog, RhoC, which has been implicated as an important pro-tumor metastasis molecule, is also dispensable for K-RasG12D-induced tumorigenesis." (PMID 26030593, 2015). "Immunofluorescent analysis of paraffin-embedded SCC tissue sections for RhoC expression showed the presence of invading cells in the adjoining blood vessels and at the periphery of the tumour, underlining the importance of RhoC to invasion." (PMID 19953094, 2010). "Among 668 genes that were differentially expressed between SLHCC and NHCC, RhoC gene was selected for further study because of its potential association with tumour metastasis." (PMID 15150600, 2004). "Of particular interest among 668 genes that were differentially expressed is the RhoC gene, whose expression is higher in highly invasive NHCC than in less invasive SLHCC since RhoC expression has been implicated in tumour metastasis." (PMID 15150600, 2004). "Perhaps this mechanism may relate to the ability of RhoC to enhance motility or to a change in the tumor microenvironment associated with RhoC-mediated EMT in tumor cells." (PMID 38807216, 2024). "This led us to conjecture that factors extrinsic to the cancer cells might explain IBC’s pronounced metastatic propensity; thus, we tested whether tumor-associated macrophages could be contributing to the phenotype through stimulation of RhoC." (PMID 27991524, 2016). "Indeed, RhoA and RhoC have been shown to be involved in different stages of tumor progression such as loss of cell polarity and cell junctions, intravasation and vascularization." (PMID 24587105, 2014). "Our results suggest that PRL-3 may mediate some tumorigenic functions of Src, particularly those associated with control of small GTPases, such as RhoC, and tumor cell motility and invasion." (PMID 23691193, 2013). "Whether Rgnef signaling connections linked to tumor progression involve RhoA or RhoC remain unknown." (PMID 22649559, 2012).
tumor (continued). "Deletion of RhoC from mice has been observed to reduce the frequency and growth of tumors, which might suggest that activating mutations might promote tumor formation, but further analysis of mutations in these family members is required to determine their functional relevance." (PMID 27104658, 2016). "These cells accumulate at sites of vascular remodeling rather than intact vessels, secreting VEGF to induce the opening of remodeled vessels, which serve as entry points for RhoC-expressing tumor cells to penetrate the vessel wall and enter the circulation." (PMID 40995371, 2025). "We have also identified specific enzyme targets of ambrosin, such as EGFR and RhoC, which are of interest due to their role in the metastatic progression of several tumor types." (PMID 40754248, 2025). "In CRC, miR-10b-5p is upregulated, enhancing cell migration and invasion by targeting the tumor suppressor HOXD10 and increasing RHOC expression, thereby supporting tumor aggressiveness." (PMID 39796267, 2025). "Due to EGFR's role in the regulation of RhoC during tumor cell migration and invasion, RhoC GTPase was selected for further study." (PMID 40754248, 2025). "miR-493, as a tumor suppressor miRNA, suppresses cell motility by downregulating RhoC and FZD4 in BLCA." (PMID 39329952, 2024). "Along with RhoC, also the Rho GTPase Rac1, has been reported to actively sustain the tumor cell invasive behaviour and to activate YAP." (PMID 39495612, 2024). "The overexpression of RhoA and RhoC can disrupt cell-cell junctions and induce the migration of tumor cells promoting the adhesions between cells and the extracellular matrix." (PMID 35793608, 2022). "Overall, the knockdown of RhoC expression gave rise to a significant reduction in the tumor area in the xenografted tongue and lymph node tissues, and similarly the relative lymph node metastatic rate was also reduced to lower than that of the control group." (PMID 33519932, 2021). "In a recent study, miR-302e targets circRhoC—a putative circular RNA (circRNA) emerging from RhoC mRNA—as a tumor suppressor." (PMID 34627249, 2021). "In particular, RhoC overexpression is associated with the metastatic behavior of HNSCC, whereas reduced RhoC expression significantly weakens tumor mobility and invasion." (PMID 33519932, 2021). "Although Rho GTPases, such as RhoA, RhoB, RhoC, and RhoE, promote tumor metastasis, the main roles of Rho GTPases remain unidentified." (PMID 33406809, 2021). "Ras homolog family member C (RhoC) is an important component of intracellular signal transduction and its overexpression has been reported to be involved in regulating tumor proliferation, invasion, and metastasis in various malignant tumors." (PMID 33519932, 2021). "HMGA2 was overexpressed in OSCC tumor tissues and further there was a close correlation between the expressions of RhoC and HMGA2 (P < 0.01, R = 0.39)." (PMID 33519932, 2021). "An in vivo tongue-xenografted nude mouse model was established to measure the effects of knockdown of RhoC on tumor cell growth and lymph node metastasis." (PMID 33519932, 2021). "RhoC expression was significantly higher in tumor tissues (n = 314) than in normal epithelial tissues (n = 30, P < 0.01)." (PMID 33519932, 2021). "Other studies have shown that the deletion of RhoC reduces the ability of tumor cells to adhere to endothelial cells and inhibits the ability of tumor cells to induce endothelial cell junction opening." (PMID 33828938, 2021). "Further mechanism studies showed that knockdown of RhoC downregulated HMGA2 expression, and HMGA2 expression was highly correlated with RhoC expression in OSCC tumor tissues via the analysis of TCGA datasets." (PMID 33519932, 2021). "The imported IgGs recognized their targets through the Fab-domains while the Fc-domains interact with TRIM21 and triggered the ubiquitin-mediated degradation of RHOC in tumor cells." (PMID 32580738, 2020).
tumor (continued). "Farnesyl transferase inhibitors (FTIs), previously shown to modulate tumor growth in Ras-transformed tumor cells, were able to reverse the phenotype induced by RhoC in IBC cells." (PMID 32883032, 2020). "We measured the protein expression levels of RNF180 and RhoC in 113 pairs of tumor and adjacent non-tumor tissues by IHC." (PMID 33082325, 2020). "The size and weight of the subcutaneous tumor transfected with shRNA RhoC was significantly decreased than that in tumor transfected with an empty vector." (PMID 33082325, 2020). "The isoforms RhoA, RhoB and RhoC constitute the Rho-like group whose RhoA and RhoC promoting tumor growth while RhoB is a tumor suppressor." (PMID 31983155, 2020). "More importantly, stable expression of RhoC increased tumor formation compared with control HME cells in nude mice, indicating that RhoC is sufficient for cellular transformation." (PMID 32992837, 2020). "Several reports cumulatively suggest that RhoC regulates numerous steps of tumor progression, including proliferation, EMT, invasion, intravasation, extravasation, anoikis resistance, angiogenesis and metastasis." (PMID 31340863, 2019). "Several groups have reported that RhoC inhibitors have a profound effect on carcinoma phenotypes in vitro, using both cell lines and tumor biopsy-derived cells." (PMID 31340863, 2019). "While RhoC has an important contribution to metastasis, RhoB has been reported, using mice models, to be a tumor suppressor." (PMID 31340863, 2019). "In this context, we discuss the role of RhoC which has contributed to several phenotypes during tumor progression." (PMID 31340863, 2019). "We show that RhoC contributes to radiation response in tumor cells by regulating the expression of important genes involved in DNA repair machinery." (PMID 31488179, 2019). "Another signaling pathway that has been shown to contribute extensively to tumor progression in several tumor types is the Ras homolog gene family member C (RhoC) signaling pathway." (PMID 31340863, 2019). "We have earlier reported that RhoC regulates several tumor phenotypes, and in this study, we extend the role of RhoC to radioresistance mediated through transcriptional regulation of DNA repair machinery." (PMID 31488179, 2019). "Assessment of the expression of RhoC and ROCK2 in tumor-derived sections showed that both RhoC and ROCK2 were coexpressed in a subpopulation of tumor cells." (PMID 31488179, 2019). "Marsdenia tenacissima modulates the CCR5-CCL5 axis, FAK, and RhoC genes that are involved in tumor invasion and metastasis." (PMID 31341493, 2019). "Enhanced expression of RhoC conferred radioprotection on the tumor cells while inhibition of RhoC resulted in sensitization of cells to radiation." (PMID 31488179, 2019). "The observation which was equally important to note was the expression of RhoC in nuclear compartments of the tumor cells." (PMID 31488179, 2019). "We next examined the correlation of tumor level of Pin1, RhoA and RhoC transcripts with the clinicopathological parameters of the HCC patients." (PMID 31324164, 2019). "Not only does RhoC regulate tumor growth, EMT, migration, invasion, and metastasis, it also regulates angiogenesis in tumors." (PMID 31340863, 2019). "Tumor angiogenesis plays an important role in disease progression, and RhoC has been previously found to be expressed in vascular endothelial cells (VECs); however, its role in tumor angiogenesis requires clarification." (PMID 31062507, 2019). "Considering that RhoC expression modulated radiation resistance of the tumor cells, we examined the changes in RhoC expression in the irradiated cells." (PMID 31488179, 2019). "Given the evidence implicating RhoC in various aspects of tumor progression, this molecule seems to be an ideal druggable target." (PMID 31340863, 2019).
tumor (continued). "Nevertheless, considering that the role of RhoC in tumor progression is overwhelming, efforts must be steered towards developing siRNA, antibodies, or small molecule-based inhibitors of RhoC." (PMID 31340863, 2019). "Among the Rho family members, Ras homolog gene family member C (RhoC) has been reported to impart tumor cell plasticity and is essential for metastasis." (PMID 31681564, 2019). "RhoC, which has been shown to modulate several tumor phenotypes has been investigated in this report for its role in radioresistance." (PMID 31488179, 2019). "Adenoviral-mediated combined delivery of RhoA and RhoC in colorectal carcinoma reduced 37% of tumor volume." (PMID 29861465, 2018). "The survival rate after 30 days of treatment was approximately 85% for anti-RhoC siRNA-treated group, indicating that lipofectamine mediated anti RhoC siRNA had a significant effect on tumor growth reduction as well as survival rate enhancement." (PMID 29861465, 2018). "Mice treated with anti-RhoA siRNA (tumor volume, 200 mm3) and anti-RhoC siRNA (tumor volume, 600 mm3) showed less tumor growth than in the control group (1300 mm3)." (PMID 29861465, 2018). "RhoA and RhoC have been suggested in many studies to contribute positively to tumor development, but the role of RhoB in cancer remains elusive." (PMID 29385717, 2018). "The relative tumor volume for anti-RhoC siRNA was 3.4, whereas it was approximately 5.2 for both control and untreated siRNA, demonstrating 35% reduction of tumor volume in contrast to the control group." (PMID 29861465, 2018). "Recombinant adenovirus-based shRNA-targeted RhoA and RhoC (Ad-RhoA-RhoC) were synthesized and subjected to animal studies for evaluating anti-tumor efficacy." (PMID 29861465, 2018). "RNAi therapy targeted to RhoA and RhoC genes is supposed to be more effective to suppress tumor growth than conventional therapy." (PMID 29861465, 2018). "The immunohistochemistry assay showed that E2F1 and RhoC expression were upregulated in the tumor xenograft tissue from nude mice of the E2F1 group when compared to the control group (P < 0.05)." (PMID 28146423, 2017). "Immunohistochemistry showed that E2F1 and RhoC expression were downregulated in the tumor xenograft tissues of the miR-519d group as compared to the control." (PMID 28146423, 2017). "Immunohistochemical analysis demonstrated that the expression of RhoC in the subcutaneous xenograft of nude mice in the lncRNA ABHD11-AS1-transfected group was significantly higher than that in the tumor tissues of nude mice in the control group." (PMID 28818073, 2017). "This is the first study to demonstrate the role of RhoC in the tumor-promoting effects of the lncRNA ABHD11-AS1." (PMID 28818073, 2017). "The Rho family of GTPases is composed of RhoA, RhoB and RhoC and regulates the cytoskeleton, playing essential roles in cell polarity, division, proliferation, apoptosis and tumor cell metastasis." (PMID 28741985, 2017). "This fits to our results: CNF toxins induce a broad invasive gene signature in contrast to RhoC induction alone, through which tumor-control mechanisms become active as well." (PMID 29152087, 2017). "A growing number of reports focus on RhoC as an essential factor for invasion and metastasis of various types of tumor cells, whereas RhoA rather seems to play a role for proliferation instead." (PMID 29152087, 2017). "Further, it seems that P70s6k, MMP2, and BCL-xL are downstream molecules of RhoC that are closely involved in the formation, metastasis and apoptosis of tumor cells." (PMID 28818073, 2017). "Immunohistochemical analysis and Western blot demonstrated a significant reduction of RhoC expression in the HSA-372 group compared with the control group in nude mice tumor tissues (P < 0.05)." (PMID 26673619, 2016). "Our findings revealed that YMO1 predicts favorable prognosis and the data suggest that YMO1 suppresses tumor invasion and metastasis by inhibiting RhoC activity." (PMID 27487132, 2016).